CDC7 (cell division cycle 7)
Diseases named in the same sentence as CDC7 in open-access papers (continued):
Sharing a sentence is not in itself a finding about the gene and the disease.
melanoma (6 papers, 2019 to 2025). A malignant, usually aggressive tumor composed of atypical, neoplastic melanocytes. "CDC7 has been shown to be overexpressed and associated with poor prognosis in various cancers including melanoma." (PMID 31578454, 2019). "Taken together, CDC7 overexpression and downregulation of miR-3613-3p were associated with Vemurafenib resistance in BRAFV600E- bearing melanoma cells." (PMID 31578454, 2019). "In the present study, we found an association between lower expression of miR-3613-3p and ERK1/2 and CDC7 hyperactivation in resistant melanoma cells." (PMID 31578454, 2019). "Herein, we report that CDC7 was overexpressed in the cytoplasm of melanoma cells compared to normal skin and its expression was correlated with age, gender and tumor staging." (PMID 31578454, 2019). "We performed exosomes-associated microRNA profiling and functional assays to determine the role of CDC7 in drug resistance using Vemurafenib-sensitive and resistant melanoma cells." (PMID 31578454, 2019). "To further understand the link between CDC7 and MAPK pathway in Vemurafenib resistance melanoma, we tested the effect of Vemurafenib treatment on CDC7 expression in parental and resistant melanoma cells harboring BRAFV600E." (PMID 31578454, 2019). "The immunohistochemical score of cytoplasmic CDC7 was high in 39/92 (42.4%), moderate in 43/92 (46.7%) and low in 10/92 (10.9%) of melanoma specimens." (PMID 31578454, 2019). "To validate the in vitro studies of overexpression of CDC7 in human melanoma tissues, we performed IHC on melanoma and normal skin tissues." (PMID 31578454, 2019). "In melanoma cells, a sustained CDC7 expression and associated MCM2–7 activation were observed in vemurafenib-resistant cells, and the CDC7 inhibitor TAK-931 was suggested as a therapeutic option for vemurafenib-resistant melanoma cells." (PMID 33801812, 2021). "In addition, melanoma specimens procured from patients with vemurafenib resistance will assist to better understand the role of CDC7 in drug resistance." (PMID 31578454, 2019). "Accordingly, we aimed to investigate whether the suppression of CDC7 could be an alternative therapy for resistant melanoma cells to overcome Vemurafenib resistance." (PMID 31578454, 2019). "This suggests the biological role of CDC7 in developing resistance in CDC7-positive melanoma cells, and its inhibition could be a potential alternative therapy in Vemurafenib resistant melanoma cells." (PMID 31578454, 2019). "The Cell division cycle 7-related protein kinase (CDC7), a known pro-cell-cycle-progression factor has been found overexpressed in melanoma." (PMID 40862737, 2025). "However, no further validation of CDC7 as a diagnostic marker for melanoma has been reported." (PMID 40700516, 2025). "We utilized recent CDC7 inhibitor, TAK-931, as a therapeutic option to circumvent the challenge of developed Vemurafenib resistance in melanoma cells." (PMID 31578454, 2019). "This study assessed CSPG4 expression in benign nevi (BN), dysplastic nevi (DN), and superficial spreading melanomas (SSM), comparing it with PRAME (PReferentially expressed Antigen in MElanoma) and evaluating the cell division cycle 7‐related protein kinase (CDC7) and the proliferation marker Ki67." (PMID 40700516, 2025). "Although various CDC7 pharmacological inhibitors have been developed exhibiting substantial antitumor activity as a single agent, no studies have been conducted on CDC7 inhibition as an alternative targeted therapy in BRAF inhibitors-resistant melanoma cells." (PMID 31578454, 2019). "This implies that CDC7 and MAPK pathway are interrelated, and CDC7 may be affected by Vemurafenib treatment in melanoma cells." (PMID 31578454, 2019). "The cytosolic staining of CDC7 in melanoma tissues was higher (p = 0.0032) compared to normal skin tissues and had a trend of significance between Stage I and III (p = 0.0763)." (PMID 31578454, 2019).
melanoma (continued). "Thus, we aimed to elucidate the biological role of CDC7 in promoting Vemurafenib resistance and the anticipated benefits of dual targeting of BRAFV600E and CDC7 in melanoma cells." (PMID 31578454, 2019). "However, no previous studies have been conducted on CDC7 inhibition as an alternative targeted therapy in Vemurafenib-resistant melanoma cells." (PMID 31578454, 2019). "Similar to CDKs, CDC7 may have a regulatory role on ERK1/2 activity in melanoma cells, which has not been established yet." (PMID 31578454, 2019). "Treatment of cells with Vemurafenib precluded CDC7 expression and ERK1/2 activity in parental, but not in resistant melanoma cells." (PMID 31578454, 2019).
oral squamous cell carcinoma (5 papers, 2015 to 2022). "In another study, knockdown of CDC7 in oral squamous cell carcinoma reduced MCM2 and ERK1/2 phosphorylation but promoted Akt phosphorylation." (PMID 31578454, 2019). "High expression of Cdc7 protein correlates with poor prognosis in patients with diffuse large B-cell lymphoma and is a marker of resistance to DNA-damaging agents in oral squamous cell carcinoma." (PMID 26208856, 2015). "Our results showed that most of oral cancer-derived cells had a higher protein level of Cdc7-Dbf4 and ATR-HSP90-HCLK2 complex than normal human oral keratinocytes (HOK), suggesting that Cdc7-Dbf4 and ATR-HSP90-HCLK2 complex are overexpressed in Oral Squamous Cell Carcinoma (OSCC)." (PMID 29209046, 2017).
cervical cancer (4 papers, 2017 to 2022). A primary or metastatic malignant neoplasm involving the cervix. "With comprehensive bioinformatics combined with clinical and cellular function analysis, CDC7 is important to the development of cervical cancer." (PMID 33763482, 2021). "By using TCGA database to query the differential expression of differential genes in cervical cancer, it was found that CDC7 was highly expressed in cervical cancer." (PMID 33763482, 2021). "The expression of differential CDC7 in cervical cancer and normal cervical tissues was compared by immunohistochemistry and extraction of RNA and quantitative reverse transcription-polymerase chain reaction (qRT-PCR)." (PMID 33763482, 2021). "Real-time quantitative RT-PCR results showed that the expression of CDC7 in siCDC7 and siNC transfected cervical cancer cell lines (Hela and SiHa), and the difference between the two groups was statistically significant (P < 0.05)." (PMID 33763482, 2021). "Experimental results can confirm that CDC7, as an oncogene, plays a significative role in the progression as well as development of cervical cancer." (PMID 33763482, 2021). "Using TCGA database to query differential expression of differential genes in cervical cancer, the CDC7 gene was found to be highly expressed." (PMID 33763482, 2021). "The role of CDC7 in cervical cancer HeLa and SiHa cell lines was verified by cell functional experiments." (PMID 33763482, 2021). "CCK-8 experiments showed that CDC7 downregulation significantly inhibited cervical cancer cell line (Hela and SiHa) proliferation." (PMID 33763482, 2021). "This study suggests that, with comprehensive bioinformatics combined with clinical and cellular function analysis, CDC7 is important to the development of cervical cancer." (PMID 33763482, 2021). "From this finding, it is clear that CDC7 plays a significant role in the development about cervical cancer." (PMID 33763482, 2021). "Although some research on CDC7 exists, its clinical significance and diagnostic value in cervical cancer have not been previously studied." (PMID 33763482, 2021). "Cell function tests demonstrated that inhibition of CDC7 expression could inhibit the proliferation and migration of cervical cancer HeLa and SiHa cells and promote apoptosis." (PMID 33763482, 2021). "Therefore, we first analyzed the expression of CDC7 in cervical cancer tissue by immunohistochemistry and qRt-PCR and found that it was significantly higher than normal cervical tissue." (PMID 33763482, 2021). "Genetic screening revealed differential expression of CDC7, which may be related to the development of cervical cancer." (PMID 33763482, 2021). "CDC7 was a potential biomarker in the early diagnosis of cervical cancer, and inhibition of its expression could prevent the proliferation and migration of cervical cancer cells and promote apoptosis." (PMID 36483932, 2022). "Capitalizing upon and targeting Minichromosome maintenance protein complex - specifically the MCM2, MCM4 and MCM6 subunits, ZWINT and CDC7 for experimental validation, may provide valuable insights in understanding and detection of progressing cervical neoplasia to cervical cancer at an early stage." (PMID 30150654, 2018). "Real-time quantitative RT-PCR results showed that the expression of CDC7 in cervical cancer tissues was upregulated compared with normal cervical tissues, and the difference between the two groups was statistically significant (P < 0.05)." (PMID 33763482, 2021).
colon cancer (4 papers, 2012 to 2025). "The crucial role of CDC7 in colon cancer cells was also demonstrated by the further in vivo verification that the combination of oxaliplatin and XL413 greatly reduced the formation of xenograft tumors." (PMID 40136426, 2025).
diffuse large B-cell lymphoma (4 papers, 2015 to 2025). "Many human primary tumors and cancer cells, such as breast, colon, lung, epithelial ovarian, and diffuse large B-cell lymphoma, exhibit overexpression of CDC7 when compared to matching normal tissues." (PMID 40136426, 2025). "In contrast to corresponding normal tissues, it has been demonstrated that CDC7 is overexpressed in a variety of human primary tumors and carcinomas, such as breast, colon, lung, epithelial ovarian, and diffuse large B-cell lymphomas." (PMID 40136426, 2025).
glaucoma (4 papers, 2012 to 2024). Increased pressure in the eyeball due to obstruction of the outflow of aqueous humor. "Finally, CDC7 (cell division cycle 7) was identified as a central node in our analysis, and polymorphisms of CDC7/TGFBR3 have been associated with glaucoma, along with visual field progression and a reduction in the thickness of the retinal nerve fiber layer of glaucoma patients." (PMID 39458974, 2024).
lung adenocarcinoma (4 papers, 2020 to 2024). A carcinoma that arises from the lung and is characterized by the presence of malignant glandular epithelial cells. "Finally, to examine the relationship between lncRNA perturbators and lncRNA-perturbated mRNAs, we overexpressed lncRNA SNHG7 and TUG1 in the A549 lung adenocarcinoma cell line and experimentally validated their function to remarkably enhance the expression of PNMA2 and CDC7 respectively." (PMID 32846981, 2020).
pancreatic cancer (4 papers, 2016 to 2025). "Taken together these data highlight the highly specific nature of the cancer-cell-specific killing following Cdc7 targeting and therefore make it a potentially powerful target in the treatment of advanced pancreatic cancer." (PMID 26921250, 2016). "We have shown via immunohistochemistry that pancreatic cancer specimens contain significantly higher expression levels of the target protein Cdc7 than resected tissue from patients with benign pancreatic disease." (PMID 26921250, 2016). "It was found that when the Cdc7 levels were assessed in biopsy samples and in resection samples for pancreatic cancer, higher expression was seen in the resection samples." (PMID 26921250, 2016). "Secondly Cdc7 kinase was targeted in Capan-1 and PANC-1 pancreatic cancer cell line models using either an siRNA against Cdc7 or alternatively a small molecule inhibitor (SMI) of Cdc7 (PHA-767491)." (PMID 26921250, 2016). "Furthermore, targeting of Cdc7 in pancreatic cancer cell line model systems with either CDC7 siRNA or alternatively Cdc7 SMI inhibitors can induce potent cancer cell-specific killing." (PMID 26921250, 2016). "Here we investigate Cdc7 as a novel therapeutic target in pancreatic cancer." (PMID 26921250, 2016). "Furthermore, we have also shown that the expression of Cdc7 strongly correlates with 3 other markers for cell cycle progression (Mcm2, geminin and phosphohistone H3) in pancreatic cancer." (PMID 26921250, 2016). "Interestingly, PRMT5 inhibition induced DNA replication stress in pancreatic cancer, and coadministration of PRMT5 inhibitor with CDC7 inhibitor XL413 exhibited promising therapy value." (PMID 40384988, 2025).
prostate carcinoma (4 papers, 2018 to 2025). A carcinoma that arises from epithelial cells of the prostate gland. "In summary, our study demonstrated that CDC7 is overexpressed in advanced prostate cancer, and that depletion of CDC7 caused significant impairment in cell growth in vitro and in vivo." (PMID 41413594, 2025). "Functional studies revealed that depletion of CDC7 impaired the proliferation, migration, and invasive capacity of advanced prostate cancer cells in vitro and suppressed tumor growth in vivo." (PMID 41413594, 2025). "In this study, we demonstrated that CDC7 is highly expressed in the majority of advanced prostate cancer cell lines, patient-derived xenografts (PDXs), and adeno-CRPC and NEPC patient samples." (PMID 41413594, 2025). "Collectively, our findings demonstrate that CDC7 is a regulator of tumor progression in prostate cancer and represents new therapeutic target in advanced prostate cancer." (PMID 41413594, 2025). "Inhibition of CDC7 significantly decreased cell proliferation and invasion of prostate cancer cell lines." (PMID 41413594, 2025). "TAK-931 treated prostate cancer cells exhibit an abnormal cell cycle profile, suggesting that CDC7 inhibition induces replication stress and promotes apoptosis." (PMID 41413594, 2025). "Inhibition of CDC7 in prostate cancer cell lines and xenograft models led to cell cycle arrest at G2/M, induction of apoptosis, and inhibition of migration and invasion." (PMID 41413594, 2025). "CDC7 is a kinase that regulates DNA replication and is found elevated during neuroendocrine transdifferentiation in lung and prostate cancer." (PMID 41413594, 2025). "In this study, we demonstrate that CDC7 is highly expressed in treatment-resistant prostate cancer, with even higher levels observed in treatment-resistant prostate cancer with neuroendocrine phenotype (NEPC)." (PMID 41413594, 2025). "We found that the majority of prostate cancer cell lines express high levels of CDC7 transcripts when compared to a benign prostate hyperplasia (BPH-1) cell line and a transformed prostate cell line with low malignant potential, WPE1-NA22." (PMID 41413594, 2025). "Downregulation of CDC7 significantly reduces prostate cancer cells growth and invasion in vitro and silencing CDC7 suppresses prostate tumor growth in vivo." (PMID 41413594, 2025). "Since CDC7 is involved in initiating DNA replication, we utilized EdU, a pyrimidine analog, to measure de novo DNA synthesis in xenograft tumors derived from shCDC7 prostate cancer cell lines." (PMID 41413594, 2025). "In prostate cancer model systems, CDC7 promotes the differentiation of adeno-CRPC into NEPC24." (PMID 41413594, 2025). "Importantly, forced expression of stabilized MYC (MYCT58A) rescued NE transformation in prostate cancer models following treatment with a CDC7 inhibitor, implicating MYC as a key downstream effector of CDC7 during NE transformation." (PMID 39858043, 2025). "Furthermore, we demonstrate that the inhibition of CDC7 using TAK-931, a selective CDC7 inhibitor, significantly reduces the proliferation, migration, and invasion of aggressive prostate cancer cells." (PMID 41413594, 2025). "Our data demonstrate that TAK-931 could have a role in treating advanced prostate cancer, particularly adeno-CRPC and NEPC models that exhibit high expression of CDC7." (PMID 41413594, 2025).
prostate carcinoma (continued). "Elevated CDC7 and MCM helicase expression levels in these cell models, especially the CDC7 direct target MCM2 subunit, correlate with higher proliferative rates observed in clinical prostate cancer with disease progression." (PMID 41413594, 2025). "To test whether prostate cancer cells are dependent on CDC7 activity for growth and evaluate its potential as a therapeutic target, we evaluated the effects of TAK-931, a CDC7-specific inhibitor, on prostate cancer cell growth." (PMID 41413594, 2025). "However, depletion of CDC7 in our advanced prostate cancer cell line led to a decrease in TGF-β1, SMAD3, and MMP9 expressions and therefore targeting CDC7 could also be a method to inhibit TGF-β driven metastasis caused by ADT." (PMID 41413594, 2025).
small cell lung carcinoma (4 papers, 2020 to 2024). Small cell lung cancer (SCLC) is a highly aggressive malignant neoplasm, accounting for 10-15% of lung cancer cases, characterized byrapid growth, and early metastasis. "In chemo-resistant small cell lung cancer, CDC7 possibly acts as synergistic target." (PMID 38725484, 2024). "Accordingly, another CDC7 inhibitor, XL413, has also been reported to promote tumor infiltration of immune cells in genetically engineered mouse small-cell lung cancer models." (PMID 37980406, 2023).
frontotemporal dementia (3 papers, 2021 to 2024). Frontotemporal dementia (FTD) comprises a group of neurodegenerative disorders, characterized by progressive changes in behavior, executive dysfunction and language impairment, as a result of degeneration of the medial prefrontal and frontoinsular cortices. "CDC7 has been also found to phosphorylate the transactive response DNA binding protein of 43 kDa (TDP-43), leading to its aggregation and accumulation in the motor neurons of some amyotrophic lateral sclerosis (ALS) and frontotemporal dementia (FTD) patients." (PMID 38205514, 2024).
myeloma (3 papers, 2013 to 2023). "However, only two reports have appeared in the literature concerning CDC7 inhibition in myeloma cells." (PMID 27655636, 2016). "The activity and mechanism of action of the dual CDC7/CDK9 inhibitor PHA-767491 was assessed in a panel of multiple myeloma cell lines, in primary samples from patients, in the presence of stromal cells and in combination with drugs used in current chemotherapeutic regimens." (PMID 24202326, 2013). "In one, PHA-767491, an inhibitor of both CDC7 and CDK9, demonstrated anti-myeloma activity both in cells obtained from patients and in cell cultures." (PMID 27655636, 2016). "In the present study we have shown that the prototype of an emerging class of kinase inhibitors targeting both CDC7 and CDK9 kinases has cell death inducing activity in myeloma cellular models." (PMID 24202326, 2013). "We report that in all conditions myeloma cells undergo cell death upon PHA-767491 treatment and we report an overall additive effect with melphalan, bortezomib and doxorubicin, thus supporting further assessment of targeting CDC7 and CDK9 in multiple myeloma." (PMID 24202326, 2013).